PGR (progesterone receptor)
Diseases named in the same sentence as PGR in open-access papers (continued):
Sharing a sentence is not in itself a finding about the gene and the disease.
breast cancer (continued). "However, one study has shown that patients with breast cancer have a higher risk of subsequent endometrial cancer regardless of ER or progesterone receptor (PR) status." (PMID 29556910, 2018). "Therefore, PgR may be a useful indicator for classifying ER-positive/HER2-negative breast cancer between the luminal A-like subtype and B-like subtype." (PMID 28532429, 2017). "Gallen consensus meeting of 2015, they showed that hormone receptor-positive/HER2-negative breast cancer may be divided into the luminal A-like type (high ER/PgR and clearly low Ki67), luminal-B like type (low ER/PgR and clearly high Ki67), and intermediate type." (PMID 28532429, 2017). "Breast cancer (BrCa) is the most common malignancy among women and is clinically stratified into three major types depending on the expression of the estrogen (ER) and progesterone receptor (PR), or amplification/overexpression of the receptor tyrosine kinase (RTK) HER2/neu." (PMID 28422745, 2017). "Breast cancer is a heterogeneous form of cancer with various biological characteristics, and it is classified into various clinical subtypes based on the presence or absence of the estrogen receptor (ER), progesterone receptor (PgR), and human epidermal growth factor receptor-2 (HER2)." (PMID 28851309, 2017). "Herein, the aim of this study was to evaluate the expression of ER and PgR, their distribution, and their correlation with classic clinicopathologic prognostic parameters (age, menopausal status, histologic type, and grade) to enhance the breast cancer patients’ medical care." (PMID 28173783, 2017). "It is important to note that the role of PgR expression in breast cancer cells remains not fully elucidated, since PgR expression is influenced by the estrogen milieu and it has been reported that the lack of PgR in ER+ tumors is associated with worse survival." (PMID 28356061, 2017). "Breast cancer is known to be a heterogeneous disease, and the different subtypes can be defined by the immunohistochemical (IHC) approach based on oestrogen receptor (ER), progesterone receptor (PR), and human epidermal growth factor receptor 2 (HER2) and Ki-67 expression levels." (PMID 28588280, 2017). "For instance, significant differences in histologic grade (p < 0.001) and PgR expression (p < 0.001) were reported between the Luminal A and B types, leading to the conclusion that different management guidelines should be considered for these two breast cancer types." (PMID 28356061, 2017). "However, the anticancer effects of ID extract on breast cancer cells classified as estrogen receptor (ER), progesterone receptor (PR), and human epidermal growth factor receptor 2 (HER2) are still unknown." (PMID 28134814, 2017). "Clusterin expression is altered in different cancers, including overexpression in human breast carcinoma, which is associated with increased tumor size, progesterone receptor-negative status, and the progression from primary to metastatic carcinoma in lymph nodes." (PMID 28210565, 2017). "Low EPHA5 is associated with high tumor grade, lymph node metastasis and PgR negative status in breast cancer, indicating that down regulation of EPHA5 could be an important step in tumor progression." (PMID 26870995, 2016). "However, pathological scoring systems relate almost solely on studies of the primary tumor tissues such as the most prominent predictive markers in breast cancer, the estrogen receptor (ER), the progesterone receptor (PGR) and the erb-b2 receptor tyrosine kinase (HER-2) status." (PMID 26862065, 2016). "As with breast cancer, we performed additional immunohistochemical staining for estrogen receptor (ER) and progesterone receptor (PgR), and this revealed 10 out of 32 cases showed partial or complete loss of the ER expression without PgR expression." (PMID 27419370, 2016).
breast cancer (continued). "It should be noted that our cohort comprised of high-risk early breast cancer patients that were all treated with chemotherapy (one of three regimens) and that, with regard to ER/PgR and HER2 status, both negative and positive patients were included in our study." (PMID 27695115, 2016). "Clinically, estrogen receptor (ER), along with progesterone receptor (PgR) and human epidermal growth factor receptor 2 (Her2) expression status are essential molecular markers for the assessment of adjuvant treatment options and prognosis for breast cancer patients." (PMID 27292433, 2016). "Economic evaluations in high-income countries have found that this use of trastuzumab generally provides value for money; however, its cost-effectiveness for specific subtypes of HER2+ breast cancer (defined by estrogen receptor [ER] and progesterone receptor [PR] status) is unknown." (PMID 27504960, 2016). "In this retrospective analysis, we sought to expand our previous observation that in patients with operable HER2-positive breast cancer, high co-expression of both the ER and PgR (“triple-positivity”-TP) could mitigate the effect of trastuzumab administered with adjuvant chemotherapy." (PMID 26910921, 2016). "Importantly, the MCF-7 breast cancer cell line expresses both the estrogen and the progesterone receptor, thus suggesting that concomitant inhibition of DUBs and autophagy could be used as a therapeutic option for patients whose tumors are hormone sensitive." (PMID 25784654, 2015). "Breast cancer cells bear (noun-verb agreement) different receptors on their surface and in their cytoplasm or nucleus, among these receptors the important ones are estrogen receptor (ER), progesterone receptor (PR), and human epidermal growth factor receptor 2 (HER2)." (PMID 25900239, 2015). "Breast cancer is now classified into subtypes based in theory on gene expression profiles but determined in clinical practice by the expression of estrogen receptor (ER), progesterone receptor (PR), overexpression of human epidermal growth factor receptor 2 (HER2) and the Ki67 proliferation index." (PMID 26376452, 2015). "Histologic and immunohistochemical analysis revealed that all HER2 heterogeneous breast cancers subjected to microdissection were ER-positive (as defined by the current cutoff of >1% of ER-positive cells in the whole tumor), and eight cases were also progesterone receptor (PR)-positive." (PMID 25994018, 2015). "Increased GRN expression was associated with reduced overall survival in all breast cancer patients, a trend that was statistically significant for patients with luminal A tumors, which express estrogen receptor and/or progesterone receptor but do not overexpress HER2." (PMID 26000098, 2015). "Moreover, deleting RANK from the mammary epithelium decreases incidence and delays onset of PgR-mediated mammary cancer, indicating that RANK signalling suppression might be an excellent strategy for breast cancer prevention." (PMID 26629528, 2015). "In contrast, an increased breast cancer risk associated with benzene was only seen among tumors that were both estrogen-receptor negative and progesterone-receptor negative (ER-/PR-) for which a HR of 1.45 was observed for the highest quintile of benzene concentration." (PMID 25636809, 2015). "Therefore, breast cancer subtypes as defined by differential ER, PgR, HER-2, and Ki-67 staining may display different response rates and different prognoses in the neoadjuvant setting." (PMID 26053183, 2015). "Indeed, estrogen receptor (ER) α and ObRs are coexpressed in malignant mammary tissue and breast cancer cell lines and it has been shown a positive association between serum leptin levels and elevated values of estrogen and progesterone receptor in patients with breast cancer." (PMID 25505738, 2014).
breast cancer (continued). "For example, a majority of participants in the studies on breast cancer were estrogen-receptor (ER) positive and progesterone receptor (PR) positive, and it is theoretically possible that the prognostic value of HOTAIR expression might be different in ER and PR-negative breast cancer." (PMID 25157956, 2014). "Despite the substantial advances in understanding breast cancer biology, the clinical management of women with this disease continues to rely almost solely on the tumoral expression of estrogen receptor alpha (ERα), progesterone receptor (PR) and epidermal growth factor receptor 2 (HER2)." (PMID 25288324, 2014). "As a positive control for estrogen treatment, progesterone receptor expression levels were shown to increase after estrogen treatment in MCF-7 cells This data suggests that estrogen signaling is involved in up-regulating Mcl-1 protein expression in ERα+ breast cancer cell lines." (PMID 24971890, 2014). "Our study provides the foundation for both as data suggest that an assessment of melanoma MMP-23 expression by routine immunohistochemistry may prove useful, much like using immunohistochemistry to determine the estrogen/progesterone receptor status in breast cancer." (PMID 25491880, 2014). "In addition, PgR may in the long run be downregulated through PI3K/AKT/mTOR pathway stimulation and subsequent aberrant ER signalling, leading to acquired endocrine resistance among patients with initially ER/PgR-positive breast cancers." (PMID 24131622, 2013). "Breast cancer is a complex heterogeneous disease which has traditionally been subclassified depending, amongst other factors, on the expression of different receptor proteins, such as estrogen receptor (ER), progesterone receptor (PR), and human epidermal growth factor receptor 2 (HER2)." (PMID 23820017, 2013). "In breast cancer, PARP-1 up-regulation has been associated with decreased survival and triple-negative (TN) cancers (breast tumours in which estrogen receptor [ER], progesterone receptor [PR] and human epidermal growth factor receptor 2 [HER2] are not expressed)." (PMID 24191908, 2013). "Tamoxifen (TAM) is widely used to prevent recurrence in patients with estrogen or progesterone receptor-positive breast cancer (BC) due to its estrogen receptor blocking effect." (PMID 23922954, 2013). "In this analysis, PGR expression was associated with prognosis in ER+ but not in ER- breast cancer." (PMID 23971947, 2013). "Furthermore, a number of less common serological and molecular markers have also shown prognostic evidence, such as the estrogen receptor, progesterone receptor, human epidermal growth factor receptor-2 in breast cancer and mismatch repair gene in stage II CRC." (PMID 24255664, 2013). "Contrarily, a French study reported an increase of breast cancer risk with the Western diet for ER+/positive progesterone receptor (PR+) tumors (HR 1.20, 95% CI: 1.03-1.38), and a negative association of the MD for breast cancer risk (HR 0.85, 95% CI: 0.75-0.95), especially for ER+/PR- tumors." (PMID 24267672, 2013). "Therefore, current research is focused on identifying preventive therapies for other forms of breast cancer such as human epidermal growth factor receptor 2 (HER2)-positive and triple-negative breast cancer (TNBC, breast cancer that does express ER, progesterone receptor, or HER2)." (PMID 24069582, 2013). "Unfavorable genetic variants in the rs207454 (XDH) and rs3736729 (GCLC) polymorphisms may act as predictors of outcome in negative progesterone receptor and negative estrogen receptor breast cancer patients, respectively." (PMID 23443115, 2012).
breast cancer (continued). "Results showed that the "healthy/Mediterranean" pattern was negatively associated with breast cancer risk (hazard ratio = 0.85, 95%CI 0.75 to 0.95; P = 0.003 for linear trend), especially when tumors were estrogen receptor-positive/progesterone receptor-negative." (PMID 21801436, 2011). "In the present study, we analyzed whether a GnRH-II antagonist induces apoptosis in estrogen receptor/progesterone receptor-positive MCF-7 human breast cancer cells, which have a normal expression of HER2-neu and triple-negative MDA-MB-231 human breast cancer cells in vitro and in vivo." (PMID 20630060, 2010). "The same characteristics of choline metabolite profiles were also observed in patient material from ER+/PgR+ and triple-negative breast cancer, suggesting that the xenografts are relevant model systems for studies of choline metabolism in luminal-like and basal-like breast cancer." (PMID 20716336, 2010). "However, in our study we could not detect a significant correlation between FOXM1 expression and oestrogen or progesterone receptor status in human breast cancer." (PMID 18254960, 2008). "It has since been recognised that ERα status and markers of its functionality such as progesterone receptor (PR) provide important prognostic information, are predictive of response to anti-oestrogen therapy and broadly delineate potentially different types of breast cancers." (PMID 18087287, 2008). "The standard prognostic factors currently used for primary breast cancer decision making in the United States are: involved axillary node status, histologic subtype, tumour size, nuclear grade, oestrogen and progesterone receptor (ER and PR) status, and measures of cellular proliferation." (PMID 15714204, 2005). "A number of parameters, namely lymph node metastases, tumor size, histologic grade, ER and progesterone receptor expression, lymphovascular invasion, proliferation rate, DNA content, and expression of oncogenes, have been reported to influence the prognosis of women with breast cancer." (PMID 15743504, 2005). "Studies in the MCF-7 human breast cancer cell line have shown that fulvestrant significantly suppresses cellular levels of ER protein and inhibits ER-induced expression of the progesterone receptor (PgR), the oestrogen-regulated protein pS2 and cathepsin D more strongly than tamoxifen." (PMID 15094757, 2004). "This study showed that conversion of ER, PgR and HER2 status is common during disease progression from primary breast cancer to breast cancer liver metastasis." (PMID 41511682, 2026). "At the same time, we carried out logistic regression analysis on B7H3 and compared different clinical characteristics of breast cancer patients, such as TNM stage, pathological grade, and progesterone receptor, estrogen receptor, HER2, and PAM50 status." (PMID 39735676, 2025). "Bioassays that are commonly used to diagnose different subtypes of breast cancers target specific biomarkers, mostly proteins such as hormone receptors (Human Epidermal Growth Factor Receptor 2 (HER2), Estrogen Receptor (ER), Progesterone Receptor (PR))." (PMID 40281771, 2025). "Recently, a study demonstrated that fibroblast growth factor receptor 2 (FGFR-2) interacts with progesterone receptor (PR) and STAT5 in hormone receptor-positive T47D breast cancer cells and in breast cancer patient samples." (PMID 40507264, 2025). "Luminal A, luminal B, HER-2 overexpressing, and TNBC subtypes are the main classifications for breast cancer based on the expression of particular biomarkers like Ki67, HER-2, progesterone receptor (PR), estrogen receptor (ER)." (PMID 40852484, 2025). "Estrogen receptor (ER), progesterone receptor (PGR), and erb-b2 receptor tyrosine kinase 2 (ERBB2) are three important receptors that are commonly utilized to categorize breast cancers." (PMID 40723371, 2025).
breast cancer (continued). "EMPD also shares some molecular features with breast cancer and MPD, with overexpression of HRs (estrogen receptor [ER] and progesterone receptor [PgR]) and/or HER2 (∼10% and ∼30% of patients with EMPD, respectively)." (PMID 40726246, 2025). "Currently, several molecular markers specific to breast cancer, such as HER2, estrogen receptor (ER), and progesterone receptor (PR), have been identified." (PMID 40282270, 2025). "Triple‐negative breast cancer (TNBC), which lacks oestrogen receptor (ER), progesterone receptor (PR), and human epidermal growth factor receptor 2 (HER2), accounts for approximately 20% of all breast cancers." (PMID 40032646, 2025). "Breast cancers (BC) are classified based on distinct molecular characteristics, including the expression of estrogen or progesterone receptor (HR) and whether it overexpresses human epidermal growth factor 2 (HER2)." (PMID 40344957, 2025). "Prior to NAT, ultrasound-guided core needle biopsy (CNB) is commonly used to obtain the status of estrogen receptor (ER), progesterone receptor (PR), human epidermal growth factor receptor 2 (HER2), and Ki-67 in the lesions of patients with breast cancer." (PMID 40552275, 2025). "TNBC subtype which lacks oestrogen receptor (ER) expression, progesterone receptor (PR) expression, Epidermal Growth factor receptor 2 (HER2) has been reported to be more glutamine addicted than other breast cancer subtypes." (PMID 40114244, 2025). "The results of this study demonstrate significant changes in the estrogen receptor (ER), progesterone receptor (PR), HER2 status, and Ki67 index following neoadjuvant chemotherapy (NACT) in breast cancer patients." (PMID 40786273, 2025). "Breast cancer is the most common malignancy among women worldwide, and the subtype of the particular note is TNBC, which lacks expression of estrogen receptor, progesterone receptor, and human epidermal growth factor receptor-2." (PMID 40313394, 2025). "The presence or absence of three receptors is particularly important when determining the type of breast cancer: the estrogen receptor (ESR1), the progesterone receptor (PGR), and the HER2 epidermal growth factor receptor (ERBB2)." (PMID 40143151, 2025). "When comparing ER-low (PS2) breast cancers to those with ER-int (PS3, PS4), we observed significant differences in nuclear grade, Ki-67 index, and total progesterone receptor scores, supporting the notion that ER-low exhibit behavior like TN breast cancer." (PMID 40382758, 2025). "Breast cancer is categorized into numerous subgroups based on the countenance of the human epidermal growth factor receptor 2 (HER2), progesterone receptor (PR), or estrogen receptor (ER)." (PMID 40035822, 2025). "Evaluating biomarkers, such as estrogen receptor (ER), progesterone receptor (PR), and human epidermal growth factor receptor‐2 (HER2), in pathological specimens is crucial for guiding breast cancer treatment." (PMID 41350189, 2025). "The patient was a 56-year-old premenopausal woman with estrogen receptor-positive, progesterone receptor-positive, HER2(+) left breast cancer; left axillary, left cervical, and left submandibular lymph node metastases; and multiple BMs." (PMID 40585619, 2025). "In this study, we aimed to determine the relationship between percentage of progesterone receptor expression and the likelihood of axillary metastasis in Her-2-negative, clinical T1-T2N0 luminal type breast cancer." (PMID 40283001, 2025). "Clinical practice utilizes the status of estrogen receptor (ER), progesterone receptor (PR), and HER2 hormone receptors to categorize breast cancer, enabling the optimization of personalized therapeutic strategies for each patient." (PMID 39997609, 2025). "The role of the membrane progesterone receptor is less defined, though it has been shown to activate PI3K-mediated survival in breast cancer, as reviewed by Camacho-Arroyo and colleagues." (PMID 40002193, 2025).